MIR1-2 (microRNA 1-2)
Synonyms: hsa-mir-1-2; MIRN1-2; miRNA1-2; mir-1-2
Gene: MicroRNA gene on chromosome 18 (21,829,004 to 21,829,088, reverse strand). Ensembl gene ENSG00000284453.
Gene Ontology:
Biological process: miRNA-mediated post-transcriptional gene silencing
Cellular component: RISC complex
Homologues: Orthologues: chimpanzee ptr-mir-1-2 (100% identical), macaque MIR1-2 (100% identical), pig MIR1-2 (100% identical), rabbit MIR1-2 (99% identical), tropical clawed frog xtr-mir-1a-1 (91% identical), zebrafish mir1-2 (82% identical), mouse Mir1a-2 (80% identical), Caenorhabditis elegans cel-mir-1 (66% identical), Drosophila melanogaster mir-1 (55% identical). Paralogues in human: MIR206 (72% identical), MIR1-1 (66% identical).
Diseases named in the same sentence as MIR1-2 in open-access papers:
MIR1-2 is named in the same sentence as 2 diseases in open-access papers, as found by Europe PMC text mining. Sharing a sentence is not in itself a finding about the gene and the disease. The quoted sentences say what the papers report.
atrial fibrillation (1 paper, 2013). A disorder characterized by an electrocardiographic finding of a supraventricular arrhythmia characterized by the replacement of consistent P waves by rapid oscillations or fibrillatory waves that vary in size, shape and timing and are accompanied by an irregular ventricular response. "We re-sequenced the MIR1-1, MIR1-2, MIR133A1, MIR133A2, and MIR133B genes, that encode the cardiac-enriched miRNAs, miR-1 and miR-133, in 120 individuals with familial atrial fibrillation and identified 10 variants, including a novel 79T > C MIR133A2 substitution." (PMID 23497314, 2013).
tumor (3 papers, 2021 to 2025). "The availability of organoids and spheroids may finally allow the study of downstream targets of somatostatin and IGF2 in I-NETs as well as the importance of candidate tumor genes like MIR1-2, RASSF1A, APC, or CDKN1B." (PMID 34680217, 2021). "Bioinformatics analysis using KEGG pathways enrichment, shows that Menin plays a tumor suppressor role in normal prostate model PNT1A probably through microRNAs regulation (e.g., MIR1-2; MIR16-1; let-7d) known for their tumor suppressor roles in PC." (PMID 34711954, 2022). "The functional relevance of chromosome 18 loss has been discussed longish and controversially with involvement of several tumor suppressors like DCC, Elongin A3, SMAD2, SMAD4, and MIR1-2, but so far, no conclusive results exist." (PMID 40410286, 2025).